SOD1 (superoxide dismutase 1)
Diseases named in the same sentence as SOD1 in open-access papers (continued):
Sharing a sentence is not in itself a finding about the gene and the disease.
urea cycle disorder (1 paper, 2023). A genetic inborn error of metabolism characterized by the deficiency of one of the enzymes necessary for the urea cycle. "In line with this hypothesis, sodium phenylbutyrate, a drug used to treat increased ammonia levels in patients with urea cycle disorders, has recently been approved for use in ALS patients, after demonstrating its ability to promote motor neuronal survival in an SOD1-ALS-mouse model." (PMID 37681895, 2023).
Vocal cord paralysis (1 paper, 2020). A loss of the ability to move the vocal folds. "Although described with A102T, I150T, A5V, I114P and G148S SOD1 variants, vocal cord paralysis has not been previously reported with homozygous D91A mutation." (PMID 32948071, 2020).
cancer (485 papers, 2002 to 2026). A tumor composed of atypical neoplastic, often pleomorphic cells that invade other tissues. "The implications of these SOD1 gene polymorphisms extend to various diseases such as heart failure, cancer, diabetes, Down’s syndrome, and amyotrophic lateral sclerosis owing to their roles in altered redox signaling." (PMID 38983269, 2024). "Cancer cells show alterations in proteins linked to ND (tau, amyloid-β, α-synuclein, SOD1, and TDP-43)." (PMID 39123408, 2024). "Copper-zinc superoxide dismutase encoded by SOD1 is one of the predominant intracellular antioxidant enzymes and an important target for cancer drug design." (PMID 37822927, 2023). "In the diagnosis or treatment of cancer, SOD1 gene mutations caused paralysis in mice, promoting tumor proliferation and invasion." (PMID 37759978, 2023). "Treatment with paclitaxel in the 3D epidermis model led to a reduction in SOD1 and Nrf2 gene and protein expression, which implies that paclitaxel impairs its antioxidant response, as well as in cancer-associated fibroblasts." (PMID 35163066, 2022). "In cancer cells, the dysfunction of SOD1 causes ROS-dependent cell damage which should benefit for cancer therapy." (PMID 35978820, 2022). "It is interesting to underline that DBI, HSP1, and SOD1 are cancer related proteins, as reported in the Human Atlas database." (PMID 32183175, 2020). "To illustrate the utility of PeCanPIE to disease areas outside the realm of cancer genomics, we show the classification of a variant in the superoxide dismutase 1 (SOD1) gene reported by the ALS research community in the ALSoD database." (PMID 31439692, 2019). "Mutations in the SOD1 gene have been linked to numerous human diseases and cancers." (PMID 34203465, 2021). "As a major antioxidant enzyme, SOD1 has been closely linked to cancer." (PMID 33859191, 2021). "Furthermore, somatic mutations of SOD1 are rare in cancer, and those few that do occur are mutually exclusive of those occurring for RAD54B, BLM and CHEK2." (PMID 26318585, 2015). "In addition, the increased activity of SOD1 results in a higher transformation rate of the superoxide radical, thus promoting the production of hydrogen peroxide, which is also associated with some types of human cancers." (PMID 37075346, 2023). "Pharmacological inhibition of SOD1 leads to accumulation of superoxide, increased oxidative stress, and selective cancer cell death." (PMID 40867898, 2025). "Superoxide dismutase 1 (SOD1) plays a key role in detoxifying superoxide radicals and maintaining redox balance in cancer cells." (PMID 40867898, 2025). "Studies have demonstrated that the succinylation of superoxide dismutase 1 (SOD1) promotes cancer cell proliferation; however, SIRT5 can reverse this effect by mediating desuccinylation and thereby restoring SOD1 enzyme activity." (PMID 39944690, 2025). "Seven of the identified HGs (HK2, SRSF10, SOD1, ERO1L, IRF3, MME, and SH3BP5) were associated with PE and various carcinomas." (PMID 40966654, 2025). "Tau, amyloid-β, α-synuclein, SOD1, TDP-43, and other proteins associated with nervous system diseases have also been identified in various types of solid and malignant tumors, suggesting a potential overlap in pathological processes." (PMID 39123408, 2024). "The copper-zinc superoxide dismutase 1 (SOD1) is a ubiquitously expressed cytoplasmic antioxidant enzyme, and its high expression in cancer cells maintains an elevated level of ROS homeostasis." (PMID 39350223, 2024). "As previously stated, Aβ, tau, α-syn, SOD1, and TDP-43 are key biomarkers in NDs and have been associated with cancer." (PMID 39123408, 2024). "The SOD-1 concentration was shown to predict overall cancer survival; however, the SOD activity in cancer has shown contradictory results." (PMID 39330521, 2024). "Altered SOD1 expression has also been observed in various cancers, possibly contributing to tumor growth and resistance to therapy." (PMID 39123408, 2024).
cancer (continued). "Given the promising results of DDC in inhibiting SOD1 and its potential implications for cancer therapy, including HBV‐related HCC, this study explores the combination of sorafenib and DDC as a therapeutic regimen." (PMID 39034442, 2024). "The innovative potential and novelty of our work lie in the strategic inhibition of multiple pathways to combat the complex interplay of viral gene expression and cancer progression through antioxidant gene, SOD1." (PMID 39034442, 2024). "Previous studies have reported that SOD1 is highly expressed in different types of malignant tumors and can effectively remove superoxide anion free radicals in cells and promote the growth of cancer cells." (PMID 38516703, 2024). "Inhibiting SOD1 activity in cancer cells can effectively modulate the ROS signaling pathway, impede the growth and proliferation of cancer cells, arrest the cell cycle progression, and promote apoptosis in cancer cells." (PMID 39350223, 2024). "Inhibition of SOD1 selectively promoted cancer cell apoptosis by regulating biological oxidant signaling networks." (PMID 37759978, 2023). "The patterns of 3 differentially expressed immune-associated CRGs, MAP2K2, SOD1, and VEGFA, in 3 single-cell samples of normal tissues adjacent to cancer were further analyzed as controls." (PMID 37822927, 2023). "SOD1 has been reported in various human cancer types and targeting SOD1 showed potential of inhibition of cancer growth in in vitro and in vivo studies." (PMID 37958462, 2023). "Contributions and mechanisms of their PPIs with SOD1 in cancer diseases also remain to be uncovered." (PMID 36834640, 2023). "A study has shown that a specific SOD1 inhibitor repressed cancer cell growth and promoted cancer cell cycle arrest and apoptosis by mediating the ROS changes in several cancers." (PMID 36672191, 2023). "Among the 102 feature genes, eight genes (MYLK, GADD45A, ACADM, UQCR11, TST, PTCD3, SOD1, CD151) were significantly enriched in the cancer hallmark of adipogenesis." (PMID 36905391, 2023). "Additional studies have shown that upregulation of SOD1 can potentially be used to induce cancer cell death." (PMID 37256172, 2023). "As expected, high expression of SOD1 is significantly correlated with poor prognosis for a variety of cancers, and downregulation of SOD1 can inhibit the growth of cancer cells." (PMID 36708053, 2023). "In cancer, vitamin D has a role in inducing the expression of numerous enzymes involved in ROS detoxification, including superoxide dismutase 1 (SOD1) and 2 (SOD2)." (PMID 37237997, 2023). "Double depletion of CHI3L1 and SOD1 reduced the PERK protein levels compared with the depletion of CHI3L1 cancer cells." (PMID 37215572, 2023). "Further preclinical research is needed on this SOD1 inhibitor to investigate its anticancer activity in other cancer types, improve its efficacy and pharmacokinetics, and understand the molecular mechanisms underlying its effects." (PMID 37371889, 2023). "Transcriptional upregulation of caspase 3, caspase 9, bax, and SOD1 genes confirms mitochondria- dependent apoptosis in the cancer cell lines." (PMID 37298090, 2023). "Through a literature review, we have observed that SOD1, one of the components of CKS, is overexpressed in the CK group and is associated with the development of various types of cancers." (PMID 37958462, 2023). "The notion that SOD1 depletion causes premature death in LLC carriers seems a further link between cancer cachexia and ALS that is also due to mutations in SOD1." (PMID 35611892, 2022). "It is reported that SOD1 inhibitor LD100 promotes cancer cell apoptosis via regulating ROS signal pathway." (PMID 35978820, 2022). "Especially, the detailed mechanism of cell death induced by SOD1 inhibition remains elusive in cancer cells." (PMID 35978820, 2022). "Previously, incubation of LA was shown to reduce the expression of various antioxidant enzymes (e.g., superoxide dismutase (SOD)-1/2 and catalase) on cancer cells." (PMID 35255889, 2022).
cancer (continued). "In bronchial epithelium adjacent to invasive cancer, the expression of cytoplasmic or nuclear SOD1 is significantly lower compared with its expression in the uninvolved bronchial epithelium away from cancer." (PMID 35978820, 2022). "Emerging evidences indicate that SOD1 is overexpressed in cancers and is essential to maintain cellular redox homeostasis under the condition with excessive ROS derived from the aberrant metabolism." (PMID 35978820, 2022). "Observed evidences from several groups indicate that SOD1 is upregulated in cancers and is essential to maintain cellular redox balance under the condition with excessive ROS derived from the aberrant metabolism." (PMID 35978820, 2022). "Using this inhibitor, we also systematically explored the mechanism of how SOD1 activity inhibition selectively kills cancer cells." (PMID 35011380, 2021). "In general, SOD1 is recognized as a promising anti-cancer target, and several small-molecule targeting drugs for SOD1 have already entered the preclinical and clinical development stages." (PMID 35011380, 2021). "As the major SOD, the role of SOD1 in cancer has been previously linked to its antioxidant function, and inhibition of SOD1 was shown to increase cancer cell death." (PMID 33859191, 2021). "Our data further reveal that SOD1 is localized in the nucleus, which sustains cancer cell growth by promoting hyperactive ribosome biogenesis through PeBoW complex-dependent pre-ribosomal RNA (rRNA) processing and ribosome biogenesis in KRAS-driven NSCLC." (PMID 33859191, 2021). "The rapid growth and proliferation of cancer cells always depend on higher SOD1 activity, so cancer cells are more sensitive to SOD1 inhibition." (PMID 35011380, 2021). "Nevertheless, DDC still has a wide range of anti-cancer applications, and DDC effectively inhibits SOD1 activity to kill cancer cells." (PMID 35011380, 2021). "The summary of SOD1 metal-chelating inhibition can provide a reference for the design of SOD1 inhibitors with anti-cancer effects in the future." (PMID 35011380, 2021). "s-Cysteinylation of SOD1 prevents the inhibitory action of hydrogen peroxide on SOD1,207,208 which contributes to an increased antioxidant potential of cancer cells and thereby protects them from oxidative damage." (PMID 33223534, 2021). "According to the results, MGST1, GPX3, SP1, TXNRD1, MAPK14, and SOD1 presented with CNV gains among various types of cancers." (PMID 34721758, 2021). "SOD1 is specifically required in cancer cells to counter the increased superoxide production associated with oncogene activation." (PMID 34411095, 2021). "The results of this study elucidated a new anti-cancer mechanism of OA by restraining the PSP via the SOD1/ROS/AMPK/mTORC1/macroautophagy/lysosomal pathway." (PMID 34703880, 2021). "The increase of grade of differentiation was proportional to the increase of SOD1 level as antioxidant against cancer in CRC patients." (PMID 32994983, 2020). "The increase of CRC grade is proportional to the increase of SOD1 production as an antioxidant against cancer in the human body." (PMID 32994983, 2020). "SOD1 is an enzyme involved in the antioxidant defense mechanism during a state of oxidative stress, hence, underexpression of SOD1 suggests a dysfunctional mechanism to counteract oxidative stress in cancer patients." (PMID 32942548, 2020). "SOD1 can in turn act as a nuclear transcription factor to fend off oxidative stress in cancer cells." (PMID 32938364, 2020). "The antioxidant effect of SOD1 can also provide protection for cancer cells or other dysfunctional cells." (PMID 32391354, 2020). "Literature data reported SOD1 overexpression in malignant BC cells, and the development of novel drug complexes targeting SOD activity can be considered as a promising strategy in the chemotherapy of malignant tumors." (PMID 32423132, 2020).
cancer (continued). "It has been shown that tumors often need more copper and that the copper chelator bis-choline tetrathiomolybdate (also known as SOD1 inhibitor ATN-224) inhibits complex IV activity in cancer cells." (PMID 32605023, 2020). "Our findings reveal that the LD100-mediated specific SOD1 inhibition selectively kills cancer cells via regulation of the ROS signaling network that is comprised of signaling pathways to support growth and to promote cycle arrest and apoptosis of cancer cells." (PMID 30911355, 2019). "Several antioxidant proteins are up-regulated in chemoresistance such as SOD1, SOD2, and SOD3 in oxaliplatin-resistant cancer cells or SOD1 and Prx1 in 5-FU chemoresistance." (PMID 31658599, 2019). "The specific SOD1 inhibition-mediated reduction of H2O2 content is crucial to the selective apoptosis of cancer cells." (PMID 30911355, 2019). "Overall, the specific SOD1 inhibition selectively kills cancer cells through both repressions of the ROS pathways to sustain cell growth and induction of cell cycle arrest and apoptosis." (PMID 30911355, 2019). "SOD1 is overexpressed in cancer with a major role to maintain cellular ROS under cellular critical threshold." (PMID 30925767, 2019). "In line, inhibition of SOD1 in mice was shown to inhibit angiogenesis and proliferation, making it a potential target of anti-cancer therapies." (PMID 30763370, 2019). "Out of 9 classifiers based on mtFE scores, 4 proteins (i.e. Lonp1, Sod1, Txn2 and Ogdh) were identified as potential cancer drivers in a forward genetic screen in mice, in comparison with 1 and 3 in mito and lysate data, respectively." (PMID 31061415, 2019). "The SRC proto-oncogene has been demonstrated to activate NADPH oxidases NOX1-, NOX3-, NOX4-, and NOX5-induced O2•− production in cancer models and to increase mutant SOD1 aggregate formation in ALS." (PMID 29478325, 2019). "Taken together, our study unravels a new mechanism showing that the SOD1/CPT1A axis is critical to support cancer cell growth." (PMID 29891006, 2018). "Recent studies regarding cell apoptosis showed the biological correlation between cyclin D1 and SOD1 in various human diseases, including genetic diseases and cancers." (PMID 30279365, 2018). "SOD1 is best known for its role in redox homeostasis and is often dysregulated during cancer development." (PMID 29891006, 2018). "In the context of cancer metabolism, FA oxidation has unveiled new and exciting therapeutic opportunities, to evaluate if SOD1 affects NPC cell metabolism, the key enzymes involved in mitochondrial FA metabolism were examined." (PMID 29891006, 2018). "A previous study showed that superoxide dismutase SOD1 acts as an endogenous ROS scavenger and a potential contributor to the survival of the cancer cell under conditions of high oxidative stress." (PMID 30279365, 2018). "IPA analysis of these unique up-regulated genes indicated that some genes were associated with cell transformation during cancer progression (ABL1, TRIO, FOSB, NRCAM, TRIB2 and CDK6) and others with cell survival (e.g., BCL10, BBC3, FGF8, HSPA4 and SOD1)." (PMID 29137349, 2017). "Comparing MES NORMA1-4 with MES TRIDUC1 we detected a significant increase in expression of SOD1 in cancer cells." (PMID 26968831, 2016). "Out of the two main SOD isoforms, SOD1 and SOD2, the level of SOD1 is found to be more critical in ROS mediated cancer progression." (PMID 26682000, 2016). "Accordingly, this study identifies two evolutionarily conserved SL interactions, namely BLM SOD1 and CHEK2 SOD1, and defines SOD1 as a novel candidate drug target in cancers harboring BLM and CHEK2 defects." (PMID 26318585, 2015). "The intrinsic abundance of SOD1 acetylation varied among cancer cells, and high level of SOD1 acetylation was correlated with elevated sensitivity to CPT." (PMID 26008972, 2015).